LRMDA (leucine rich melanocyte differentiation associated)
Description:
Required for melanocyte differentiation.
Synonyms: C10orf11; CDA017; OCA7
Tractability: No criterion of Open Targets' tractability assessment is met for any kind of drug.
Gene: Protein-coding gene on chromosome 10 (75,431,624 to 76,560,168, forward strand). Ensembl gene ENSG00000148655.
Subcellular location (Human Protein Atlas): Nucleoplasm; Cytosol
Gene Ontology:
Biological process: melanocyte differentiation
Cellular component: nucleoplasm
Genetic constraint (gnomAD): Loss-of-function variants: 17 observed, 26.61 expected, observed/expected ratio (o/e) 0.64, 90% interval 0.44 to 0.96. The upper end of that interval is the gene's LOEUF score, 0.96, which puts it in group 4 of 6, group 1 being the genes least tolerant of losing a copy. Missense variants: 273 observed, 282.07 expected, observed/expected ratio (o/e) 0.97, 90% interval 0.88 to 1.07. Synonymous variants: 125 observed, 114.42 expected, observed/expected ratio (o/e) 1.09, 90% interval 0.94 to 1.27.
Homologues: Orthologues: chimpanzee LRMDA (99% identical), macaque LRMDA (97% identical), rabbit LRMDA (92% identical), guinea pig LRMDA (90% identical), pig LRMDA (90% identical), mouse Lrmda (88% identical), rat Lrmda (88% identical), tropical clawed frog lrmda (69% identical), zebrafish lrmda (68% identical), dog LRMDA (56% identical), Drosophila melanogaster CG31274 (27% identical), Drosophila melanogaster MESK4 (27% identical). Paralogues in human: SNRPA1 (29% identical), LRRC72 (25% identical).
Diseases named in the same sentence as LRMDA in open-access papers:
LRMDA is named in the same sentence as 24 diseases in open-access papers, as found by Europe PMC text mining. Sharing a sentence is not in itself a finding about the gene and the disease. The quoted sentences say what the papers report.
albinism (6 papers, 2019 to 2024). A congenital disorder characterized by partial or complete absence of melanin pigment in the eyes, hair, or skin. "This study assessed previously reported coding variants in albinism genes (TYR, OCA2, TYRP1, SLC45A2, SLC24A5, LRMDA) and common intronic, regulatory variants of OCA2 in individuals with amelanotic/hypomelanotic melanoma, pigmented melanoma cases and controls." (PMID 32966289, 2020). "Autosomal recessive ocular albinism (AROA) is a term that has been used for patients with albinism with an ocular phenotype caused by mutations in TYR, OCA2, TYRP, SLC45A2, SLC24A5, or LRMDA (OCA1-7), but without a clearly defined boundary between calling a phenotype OCA or AROA." (PMID 38555393, 2024).
melanoma (5 papers, 2020 to 2025). A malignant, usually aggressive tumor composed of atypical, neoplastic melanocytes. "A nonsense mutation in LMRDA causes oculocutaneous albinism type 7 in humans, and knockout of LRMDA in a human melanoma line causes alterations in PMEL processing and in the expression of melanogenic genes, suggesting that LRMDA plays an important role in eumelanin synthesis." (PMID 37068079, 2023). "In agreement with the previous studies on RAB32 and LRMDA, we could observe a decrease in pigmentation in RAB32 CRISPR/Cas9 knock-out human melanoma MNT1 cells, as well as in a previously characterised LRMDA knock-out MNT1 cell line." (PMID 39975051, 2025).
oculocutaneous albinism type 7 (4 papers, 2022 to 2025). Oculocutaneous albinism type 7 (OCA7), formerly called OCA5, is a form of oculocutaneous albinism (OCA) characterized by skin and hair hypopigmentation, nystagmus and iris transillumination. "We reveal how LRMDA mutations, causative for oculocutaneous albinism type 7, a hypopigmentation disorder accompanied by poor visual acuity, uncouple RAB32 and Commander binding thereby establishing the mechanistic basis of this disease." (PMID 41038817, 2025). "We reveal how LRMDA mutations, causative for oculocutaneous albinism type 7 (OCA7), a hypopigmentation disorder accompanied by poor visual acuity, uncouple RAB32 and Commander binding thereby establishing the mechanistic basis of this disease." (PMID 39975051, 2025).
COVID-19 (2 papers, 2025). A disease caused by infection with severe acute respiratory syndrome coronavirus 2. "SNPs within an intronic region of LRMDA are also associated with increased susceptibility to COVID-19 in non-Europeans and with platelet aggregation phenotypes, consistent with a broader role of LRMDA in immune cells and megakaryocytes." (PMID 39975051, 2025).
diabetes (2 papers, 2022 to 2025). "Moreover, other variants of LRMDA gene were associated with metabolic phenotypes i.e. with diabetes, triglyceride levels as well as BMI and waist-to-hip ratio adjusted for BMI in the UK Biobank analysis." (PMID 36104811, 2022).
breast carcinoma (1 paper, 2025). "To elucidate the intricate roles of ADK fusion genes in HR+/HER2‒ breast cancer, we identified several distinct fusion events involving ADK with 6 different partner genes: PCDH15, SEC24C, KAT6B, RSU1, NARS2, and LRMDA." (PMID 41213951, 2025).
viral infections (1 paper, 2022). "Taken together, these data suggest that LRMDA functions downstream of TRPV2 to promote viral infections." (PMID 36261399, 2022).
X-linked ocular albinism (1 paper, 2019). "Six genes are associated with autosomal recessive OCA (TYR, OCA2, TYRP1, SLC45A2, SLC24A5 and LRMDA), and one gene, GPR143, is associated with X-linked ocular albinism (OA)." (PMID 30679655, 2019).
tumor (2 papers, 2014 to 2024). "The highest upregulated gene from the differential expression analysis was LRMDA, a melanocyte differentiation factor, suggesting an interactive role between these TAMs and the tumour cells." (PMID 38969631, 2024).
LRMDA also shares sentences with these, for which no sentence is quoted: oculocutaneous albinism (4 papers); Aland island eye disease (1); asthma (1); autosomal recessive ocular albinism (1); cancer (1); connective tissue disease (1); Digestive system disease (1); Genetic Disorders (1); glioblastoma (1); glioma (1); Griscelli syndrome (1); lysosome-related organelle disorders (1); male pattern baldness (1); Obesity (1); ocular albinism (1).